SP1 (Sp1 transcription factor)
Diseases named in the same sentence as SP1 in open-access papers (continued):
Sharing a sentence is not in itself a finding about the gene and the disease.
cancer (continued). "Acetylation of Sp1 can impact its DNA binding capacity and subsequent transcriptional regulation, thereby influencing cancer progression." (PMID 39228402, 2024). "Sp1 increases GSDME expression to ensure pyroptosis occurs during cancer cells stimulated by chemotherapy drugs, consistent with the previous report that the expression of GSDME is essential to the apoptosis-to-pyroptosis switch." (PMID 38238307, 2024). "Studies have shown that AP1G1 and SP1 are more highly expressed in cancer tissues than in normal tissues, and both are related to the invasion and proliferation of cancer cells." (PMID 39056681, 2024). "Previous studies have reported that SP1 can activate or repress the transformation of normal cells to cancer cells, thereby promoting or inhibiting cancer progression." (PMID 39749324, 2024). "Apart from ERK and ATM kinases, PI3K can participate in cancer development by promoting Sp1 phosphorylation." (PMID 39228402, 2024). "Whereas ceramides promote cancer cell apoptosis and inhibit cell proliferation and migration, SP1 promotes cell proliferation and angiogenesis." (PMID 38610937, 2024). "Nevertheless, our results indicate that hTERT can influence the Sp1 mRNA level and we believe these findings are essential for the adjustment of existing models of regulatory networks in normal and cancer cells." (PMID 39408734, 2024). "In patient samples and cancer models, Sp1 levels correlate with stage, invasive potential, and metastasis." (PMID 38540340, 2024). "This is probably because M4N induces a negative impact on cancers by its activity that influences a broad range of biological processes as a dual inhibitor of SP1 and HIF1A and makes cancers susceptible to a second anticancer drug." (PMID 39590335, 2024). "Sp1 can act on both oncogenes and tumor suppressor genes and is deeply involved in the onset and development of malignant tumors." (PMID 38466034, 2024). "Sp1 expresses strong pro-cancer functional activity and abnormal expression in numerous cancer types." (PMID 39228402, 2024). "This review systematically reviews the regulatory effects of Sp1 PTMs on cancer to provide novel ideas and strategies for cancer treatment and prevention." (PMID 39228402, 2024). "M4N also decreases the cellular content of HIF1A, another major transcription factor, in cancer cells under hypoxia, indicating that it functions as a dual inhibitor of both SP1 and HIF1A." (PMID 39590335, 2024). "In this review, the role of Sp1, Sp3 and Sp4 in the development of cancer and their regulation of pro-oncogenic factors and pathways is reviewed." (PMID 36982239, 2023). "In cancer cell studies, SP1 was considered a key mediator of CYP1B1 action, whilst CYP1B1 was shown to activate a epithelial to mesenchymal transition and Wnt/beta-catenin-signaling pathways, upregulating beta-catenin and other TFs, such as ZEB2 and SNAI1." (PMID 37511270, 2023). "This suggests that the process of cell transformation is accompanied by early induction of Sp1 and Sp3 prior to conversion of the muscle cell into a cancer cell." (PMID 36982239, 2023). "Sp1 plays an important role in CRC by regulating genes involved in all cancer-related processes, including growth factor-independent proliferation, immortality, evasion of apoptosis, angiogenesis, tissue invasion, and metastasis." (PMID 37742010, 2023). "Sp1 is responsible for the transcription of numerous genes involved in the onset and development of various cancers." (PMID 38001739, 2023).
cancer (continued). "Still, the silencing of SP1 seems to be a promising target in cancer treatment due to the observed marked decrease in cell motility and invasiveness of tumors." (PMID 37894370, 2023). "The expression of Sp1 in most cancers was higher than in para-carcinoma tissue, and high expression of Sp1 in cancers promotes cancer cell proliferation, migration, and invasion by regulating a variety of genes participating in tumorigenesis." (PMID 36860919, 2023). "Despite these facts, anticancer agents that specifically target SpTFs are not being developed currently for clinical applications, even though several small molecules that are used for cancer and other chemotherapies also downregulate/degrade Sp1, Sp3 and Sp4." (PMID 36982239, 2023). "A detailed study of the role of Sp1, Sp3 and Sp4 in cancer was investigated in multiple cancer cell lines by individual knockdown of the three genes and their combination coupled with analysis of the resulting functional and genomic effects and their overlap." (PMID 36982239, 2023). "The target genes regulated by Sp1 predominantly relate to cell proliferation and oncogenesis, which correspond to cancer’s hallmarks." (PMID 37833989, 2023). "Sp1 is also reported to induce metabolic reprogramming and promote tumorigenesis in several types of cancers." (PMID 37147632, 2023). "It total, 32 genes, which included IL6 and SP1 of the top 10 high-priority genes, were common for pathways in cancer (hsa05200) and pathways of neurodegeneration (hsa05022)." (PMID 37298337, 2023). "Sp1 can either activate or repress the conversion of normal cells into cancerous cells, thereby promoting or inhibiting cancer progression." (PMID 37147632, 2023). "SP1 belongs to the SP transcription factor family and functions in the transcriptions of many genes, which are essential for cancer development." (PMID 37686205, 2023). "In fact, it has been shown that both HIF-1 and SP1 are involved in every aspect of cancer-related cellular mechanisms." (PMID 37998757, 2023). "Here, our study provided further insight into the complex regulation of UBE2N expression in cancer progression by demonstrating that transcription factor SP1 promotes UBE2N expression at the transcriptional level via binding to the promoter of UBE2N." (PMID 36964266, 2023). "This study was the first to show that Sp1 transcriptionally regulated β-1,4-GalT-V, especially in cancer cells." (PMID 38203654, 2023). "Systems analyses of the regulatory networks in cancer have shown that SP1, HIF-1, and MYC belong to a group of TFs that function as master regulators of cancer." (PMID 37998757, 2023). "SP-1 is a gene downstream of the lncRNA/miR/mRNA axis and has been found to be regulated by lncRNA-miR crosstalk in various cancers, including lung adenoma and non-small cell lung cancer." (PMID 37189636, 2023). "SP1 is the founding member of the SP transcription factor family, which is overexpressed in several cancers." (PMID 36964266, 2023). "There is evidence that Sp1 controls genes involved in cell differentiation, the cell cycle, and apoptosis, which affect the development of numerous cancer cells." (PMID 36840005, 2023). "We confirmed the lower level of ESR1 mRNA by qPCR in 44 paired samples of cancer as compared to control endometrial tissue and lower protein levels of ERα by Western blotting with antibodies SP1 in 18 paired samples." (PMID 36769338, 2023). "There is increasing evidence that Sp1, Sp3 and Sp4 play an important role in multiple cancers and their prognostic importance spans their functional pro-oncogenic activities alone and in combination with miRNAs and lncRNAs." (PMID 36982239, 2023). "The pro-oncogenic functions of Sp1, Sp3 and Sp4 in cancer cell lines were studied in knockdown studies where silencing of each individual Sp TF decreased cancer growth, invasion and induced apoptosis." (PMID 36982239, 2023).
cancer (continued). "Sp1 plays a varied role in regulating LncRNA since Sp1 and various LncRNAs regulate each other individually or reciprocally and also cooperate with other gene products and miRNAs in cancer cells." (PMID 36982239, 2023). "EGCG negatively modulates the expression of various transcription factors such as Sp1 (Specific protein 1), AP-1 (activator protein 1), and NF-κB, finally preventing cancer formation." (PMID 37298188, 2023). "SP1, as a transcriptional factor, plays an important role in cancer development and regulates cell cycle progression." (PMID 37175660, 2023). "It is known that the activity of SP-1 regulates lncRNA in breast and colorectal cancer and promotes chemical resistance and cancer progression." (PMID 37189636, 2023). "Specificity protein 1 (Sp1) is the first identified transcription factor crucial in cancer development." (PMID 37445835, 2023). "SP1 plays a vigorous role in promoting carcinogenesis in a variety of tumors, and SP1 up-regulation was reported to predict a poor prognosis for cancer patients." (PMID 37240447, 2023). "The specificity protein (Sp) transcription factors (TFs) Sp1, Sp2, Sp3 and Sp4 exhibit structural and functional similarities in cancer cells and extensive studies of Sp1 show that it is a negative prognostic factor for patients with multiple tumor types." (PMID 36982239, 2023). "These AGEs can also activate the RAGE/ERK/SP1/matrix metallopeptidase-2 (MMP2) cascade in cancer tissues." (PMID 36890832, 2023). "Extracts from various plants were found to target Sp1, which combines with a specific DNA sequence and is overexpressed in many cancers." (PMID 35524332, 2022). "Consistent with our previous finding and published human cancer cell results, Sp1 is the strongest TF that drives Axl expression in mouse mesangial cells." (PMID 35740998, 2022). "While not hitherto applied in the clinic, some experimental evidence indicated that inhibiting Sp1 can be a feasible strategy in targeting GBM in human cancer cell lines and PDX models." (PMID 35778451, 2022). "Sp1 regulates the expression of multiple genes and its overexpression contributes to the malignant phenotype of a variety of human cancers by upregulating genes that enhance proliferation and migration." (PMID 35625703, 2022). "Our study indicates that cholesterol/EGFR/Src/Erk/SP1 axis-induced ERRα re-expression promotes survival of gefitinib and osimertinib-resistant cancer cells." (PMID 35303882, 2022). "Plicamycin is a natural polycyclic aromatic polyketide that inhibits SP1 transcription factor binding to DNA, impeding apoptosis, angiogenesis, invasion, and metastatic processes in cancer cells." (PMID 36699463, 2022). "Transfection of MCF-7 and MDA-MB-231 cancer cells with miRNA-20a, miRNA-106a and miRNA-106b antagomirs led to evident suppression in the levels of Sp1, Sp3, Sp4 and EZH2, but, simultaneously, there was an increase in the levels of ZBTB4." (PMID 36615262, 2022). "As an epigenetic factor, RBBP7 binds to histone deacetylase 1 (HDAC1) and specificity protein 1 (Sp1) to exert complicated and contradictory functions in cancer development." (PMID 35538026, 2022). "Due to its frequent implication and close correlation with cell growth, differentiation, and carcinogenesis, SP1 has been suggested as a candidate long-standing target in cancer therapy." (PMID 35590288, 2022). "We herein report that Sp1 negatively regulates metastasis and cancer stemness in E2-A549 and A549-T24 cells." (PMID 35034634, 2022). "Because CD44 is related to cancer stemness and cancer malignancy, the regulatory effect of Sp1 on the level of CD44 was studied." (PMID 35034634, 2022).
cancer (continued). "Similar to Sp1 and Sp4, Sp3 is often highly expressed in cancer cells, and knockdown of Sp3 in these cancer cells dramatically reduced cell proliferation and survival." (PMID 35019687, 2022). "A recent study showed that berberine treatment suppresses cancer cell growth by regulating miR-22 and SP1, which are downstream targets of CCND1 and BCL2 in HCC." (PMID 35723348, 2022). "Due to the discovery of Sp1 involved in the cancer suppressive effects of miR-145, we next examined the Sp1 protein level after manipulating the intracellular level of miR-145-5p in the NSCLC cells." (PMID 36499676, 2022). "Vanguard expression is maintained in cancer cells by SP1‐dependent transcription according to glucose availability and cellular adenosine triphosphate (ATP) levels." (PMID 36047643, 2022). "Sp1 transcription factor is overexpressed in many types of cancer cells including PCa and controls several genes that are involved in many cellular processes, including cell differentiation, cell growth, apoptosis, angiogenesis, and response to DNA damage." (PMID 35163245, 2022). "The specificity protein 1 (SP1) is a zinc-finger transcription factor, the overexpression of which has been correlated with poor clinical outcomes in various cancer types, including PDAC." (PMID 36038612, 2022). "In esophageal carcinoma upregulation of miR-429, by targeting both Bcl-2 and SP1, promotes apoptosis in cancer cells." (PMID 36158660, 2022). "SP1 has been described as a promising oncogene in multiple human malignancies, which exerts strong promoting effects on cancer growth, metastasis, and even chemoresistance." (PMID 35924788, 2022). "The specificity protein 1 (SP1) is a well-known transcription factor involved in cancer proliferation and metastasis and has been shown to promote tumor cell EMT." (PMID 35473752, 2022). "SP1 seems to enhance cancer progression by altering cell proliferation and invasion, according to these findings." (PMID 36005140, 2022). "Because cancer stemness characteristics are the major reason for drug resistance and cancer recurrence, which lead to a poor prognosis, the role of Sp1 in sphere formation was studied in E2-A549 and A549-T24 cells." (PMID 35034634, 2022). "SNAI1 encodes Snail-1 which regulates the mesenchymal transition of cancer, and also pro-metastatic CAFs, while SP1 is critical for the production of various ECM proteins." (PMID 35565326, 2022). "Plicamycin, an inhibitor of SP1, can inhibit tumour progression in several cancer types and has been used for the treatment of lung, breast and gastrointestinal tract cancers in phase II clinical trials, with good efficacy." (PMID 36699463, 2022). "Growing evidence has shown that Sp1 and CUL4A are both overexpressed in many cancers and are associated with a poor prognosis." (PMID 33895141, 2021). "The top 5 important TFs observed in more than 10% of all cancer genomes include SP1, RXRA, NR2F2, GABPA, and CTCF." (PMID 33647036, 2021). "Specificity protein 1 (Sp1), as one of the earliest transcription factors to be identified, regulates various cancer-related genes." (PMID 34202606, 2021). "Aberrant expression of SP1 is deemed to promote the initiation and progression of human cancers including CRC15." (PMID 34420031, 2021). "Recent studies have demonstrated that SP1, a relevant transcription factor in cancer, regulates EWSR1-FLI1." (PMID 34345016, 2021). "A total of 242 genes with a Jaspar score > 90 were selected, and a literature search confirmed 57 as potential metastasis-promoting genes, including Sp1, a master regulator of cancer metastasis." (PMID 33484377, 2021).
cancer (continued). "It has been reported that SP1 can regulate microRNA expression at the transcriptional level, while in several human cancers SP1 acts as a downstream target molecule and is posttranscriptionally modulated by miRNAs." (PMID 34905435, 2021). "Overexpression of SP1 induces the expression of several genes involved in malignant transformation of cancer cells." (PMID 34199886, 2021). "Many Sp1 targets are the hallmarks of cancer progression, including EGF on sustained proliferation/immortality, Bcl-2 on apoptosis, TSP-1 on angiogenesis, MMP9 on metastasis, and BRCA1 on DNA damage/stress response." (PMID 34830324, 2021). "We conducted this meta-analysis to elucidate the clinical significance and prognostic value of SP1 in malignant tumors." (PMID 34257529, 2021). "The overexpression of Sp1 emerges in various cancer types, e.g., human glioma, breast cancer, gastric cancer, pancreatic ductal adenocarcinoma, and thyroid tumors." (PMID 34830324, 2021). "Surprisingly, BCL2L1, E2F1, HRAS, MAPK8, MITF, RELA, and SP1 were all found in the mitophagy and cancer pathways." (PMID 34262589, 2021). "Increased TERT mRNA levels were observed after overexpression of SMYD3, while its suppression led to reduced H3K4 trimethylation within the TERT core promoter and also decreased the ability of MYC and SP1 to bind the promoter in cancer cell lines." (PMID 33802026, 2021). "This indicates SP1 and Wnt pathway form a positive feedback loop to boost the progression of cancers." (PMID 34257529, 2021). "Sp1 overexpression has been found in many cancers, including thyroid, pancreatic and breast cancers, and its expression was associated with metastatic potential and poor prognosis." (PMID 33472586, 2021). "SP1 is a general TF that is required for transcription of a large number of ‘housekeeping genes’, and it is over-expressed in many cancers." (PMID 33647036, 2021). "The classic transcription factor SP1 has been confirmed to be closely related to the expression of multiple genes and the development of multiple cancers including PDAC." (PMID 33546693, 2021). "The transcription factor SP1, which is a known regulator of the development of various cancers, including RB." (PMID 33345272, 2021). "A more comprehensive understanding of the function of Sp1 in cancer is needed to verify its potential as a therapeutic target." (PMID 33895141, 2021). "A vast number of studies indicated that small-molecule drugs and natural products (bortezomib, retinoids, aspirin, metformin, and curcumin) downregulated SP1 expression in cancer cells." (PMID 34199886, 2021). "Our paper was of great significance since it uncovered the clinical significance of SP1 for cancer patients." (PMID 34257529, 2021). "Specificity protein 1 (Sp1) is a transcription factor that is overexpressed in several cancers and regulates genes involved in cell cycle and proliferation." (PMID 34003246, 2021). "Some research has showed that Sp1 is overexpressed in cancer cells and contributes to the formation of cancer." (PMID 33767987, 2021). "Specificity protein 1 (Sp1) is a transcription factor that is frequently overexpressed in a wide variety of human cancers and contributes to malignant transformation." (PMID 33916244, 2021). "It was reported that EGFR signalling enhances IRES-mediated translation of Sp1 during tumorigenesis, and Sp1 accumulates in cancer cells." (PMID 33597819, 2021). "Accumulating proof has shown SP1 expression correlates with proliferation, migration, invasion and cell cycle in cancer cells." (PMID 34257529, 2021). "The SP1 signalling is another pathway of interest because SP1 dysregulation has been reported in many diseases and cancers." (PMID 34078370, 2021). "Kahweol produces an apoptotic effect in cancer cells by regulating cyclins, the apoptosis-related proteins Sp1 and Akt, and the ERK/JNK pathway." (PMID 34638852, 2021). "Accordingly, miR-29b, by inhibiting all cellular processes related to Sp1, can impede cancer development." (PMID 34627167, 2021).